TRPV2 (transient receptor potential cation channel subfamily V member 2)
Diseases named in the same sentence as TRPV2 in open-access papers (continued):
Sharing a sentence is not in itself a finding about the gene and the disease.
tumor (52 papers, 2013 to 2025). "The robustness of our asTCRs and their TCR-T cell derivatives, Tranilast (TRPV2 inhibitor), and their bivalent treatment were evaluated with prospective cross-reactive human-peptide variants and tumor cells." (PMID 38336680, 2024). "This TRPV2 interactome is robust and it is particularly associated with neoplasms and diseases of the nervous system." (PMID 29719613, 2018). "Because agonists of TRPV2 are implicated not only in tumor progression but also in angiogenesis, we can speculate that TRPV2 activity could be targeted in both TECs and normal ECs." (PMID 31288452, 2019). "After validation of the interactome in silico, we define a TRPV2-interactome signature combining proteomics with the available physio-pathological data in Disgenet to find interactome-disease associations, highlighting nervous system disorders and neoplasms." (PMID 29719613, 2018). "Finally, TRPV2 functional expression in tumor cells can also depend on the presence of alternative splice variants of TRPV2 mRNA that act as dominant-negative mutant of wild-type TRPV2 channels, by inhibiting its trafficking and translocation to the plasma membrane." (PMID 24709905, 2014). "Due to the differential expression of TRPV2 between tumor cells and normal cells, this strategy significantly enhances therapeutic specificity while sparing healthy tissue." (PMID 40013983, 2025). "The researchers subcutaneously administered tumor xenograft mice with HT-29 colorectal cells or their TRPV2-overexpressing derivatives into their flanks in order to evaluate the effects of anticancer phototherapy." (PMID 40548119, 2025). "RT-qPCR investigation showed a decrease in mRNA levels of stemness-associated markers as a result of the laser irradiation effect on mouse tumor tissues tested with PCNH or TRPV2–PCNH NPs." (PMID 40548119, 2025). "This dual action enables tumor cells to take up more calcium ions when the TRPV2 channel is open, leading to calcium overload within the cells." (PMID 40013983, 2025). "TRPV2 is a key marker for tumor invasion and progression,[10a] with elevated expression in tumor cells compared to normal stem cells and osteoblasts." (PMID 40013983, 2025). "Tumors derived from MDA-MB-231 cells with stable TRPV2 overexpression exhibited accelerated growth compared to the control group (Mock), as indicated by increased tumor size and weight." (PMID 39334351, 2024). "For example, the TRPV2 agonist probenecid and the TRPV2 antagonist tranilast significantly inhibit or promote the tumor growth of HepG2 xenografts in severe combined immunodeficiency (SCID) mouse models, respectively." (PMID 38397045, 2024). "Consistently, we observed a substantial decrease in Ki67 (a marker of dividing cells) levels in tumor section from TRPV2 silencing group." (PMID 39334351, 2024). "When considering the whole cohort, we observed lower TRPV2 expression in stage 1 and stage 2 tumors, while higher TRPV2 expression was evident in more advanced tumor stages, specifically in stage 3." (PMID 39334351, 2024). "This pro-tumorigenic effect of TRPV2 overexpression was further verified by the elevated expression of Ki67 in the tumor sections." (PMID 39334351, 2024). "This course was also observed in one liver cancer in vivo model, where the reduction of TRPV2 expression enhanced tumor development, while its overexpression displayed the opposite effect." (PMID 36142596, 2022). "Similar findings were also observed in xenografted mouse models when TRPV2 overexpression reduced tumor volume and promoted the differentiation of stem cells." (PMID 36142596, 2022). "Previous studies have shown that TRPV2 has important roles in the proliferation, invasion, and apoptosis of tumor cells." (PMID 35406761, 2022). "The mRNA expression of TRPV2/3 was upregulated while the expression of TRPV5/6 was downregulated in ccRCC tumor tissues." (PMID 35558077, 2022).
tumor (continued). "Our results are in line with a recent report regarding the role of TRPV2 in EC, reporting a positive correlation between elevated TRPV2 expression in tumor biopsies, increased tumor stage and shorter progression free survival." (PMID 34936030, 2021). "Altogether, these data suggest TRPV2 gene expression in the primary tumor biopsy as a valuable predictor for disease recurrence." (PMID 34936030, 2021). "Concerning TRPV1 and TRPV2, the preventing role in gliomagenesis and tumor progression has been more clearly established and characterized (see next paragraph)." (PMID 33928077, 2021). "In UC, it has been demonstrated that the expression and activity of both TRPV1 and TRPV2 affect tumor stage progression and cell differentiation." (PMID 33477303, 2021). "In this model, both TRPV2 gene expression and tumor grade remained independent predictors for disease recurrence." (PMID 34936030, 2021). "From all previous results, TRPV2 mRNA expression emerges as a strong biomarker for progressive EC, both in whole tumor biopsies and EC cells." (PMID 34936030, 2021). "As such, ROC curves showed that TRPV2 and tumor grade were the best predictors for recurrence in this data set, with AUC values of 0.707 and 0.708, respectively." (PMID 34936030, 2021). "Contrary to TRPV2, TRPC1 mRNA expression does show a strong association with tumor cell specific clinicopathological characteristics, which is reflected in the results obtained using EC cells." (PMID 34936030, 2021). "Highly expression of TRPV2 was found in 18.86% of tumor specimens, 30.19% were moderate and 50.94% stained low or negative." (PMID 32751388, 2020). "Compared with Colon-26 derived tumours, the size of TRPV2-overexpressing tumours (Colon-26-TRPV2) was reduced in a greater extent." (PMID 32807785, 2020). "TRPV2 is involved in both early and late (advanced) stages of tumor development as well as metastasis." (PMID 33376561, 2020). "Temperatures above 52 °C (TRPV2 activation threshold) occurred only in HT-29–TRPV2 tumours of the TRPV2–PCNH + laser group." (PMID 32807785, 2020). "A high TRPV2 interactome protein expression correlated with greater tumor progression, recurrence and TMZ resistance, and poor prognosis of GBM patients." (PMID 33376561, 2020). "RT-qPCR analyses of tumour tissues from mice treated with PCNH or TRPV2–PCNH nanoparticles revealed decreases in expression levels of stemness-associated markers in the latter following laser irradiation." (PMID 32807785, 2020). "The injection of TRPV2-overexpressing GSCs in a xenograft mouse model reduced tumor growth due to cell cycle arrest and increased glial differentiation." (PMID 33376561, 2020). "Whole-body fluorescence live imaging showed that ICG-labelled TRPV2–PCNH nanocomplexes accumulated at tumour xenografts, with peak accumulations at 24 h after injection." (PMID 32807785, 2020). "Similar results were also confirmed by IHC experiment using Colon-26 control and TRPV2 overexpressing tumours." (PMID 32807785, 2020). "Western blotting revealed downregulation of CD133 in nanocomplexes and laser-treated A549 tumours that were transfected with TRPV2 plasmid in situ." (PMID 32807785, 2020). "Immunohistochemical analysis in PCa patient samples confirmed TRPV2 overexpression in intratumoral ECs, showing positive expression in seven of 10 patient samples (Figure 2abii), with variable expression in tumor cells (Figure 2abii)." (PMID 31288452, 2019). "Knockdown experiments demonstrated that TRPV2 depletion suppressed tumor proliferation, cell cycle progression, and migration/invasion, and also induced apoptosis in ESCC cells." (PMID 31690728, 2019). "Our study showed, for the first time, a role for TRPV2 in tumor angiogenesis by clearly demonstrating the channel as a positive modulator of EC viability and proliferation." (PMID 31288452, 2019). "In particular, they observed a progressive reduction of both TRPV2 mRNA and protein as tumor grade increased." (PMID 31083561, 2019).
tumor (continued). "In order to evaluate the significance of TRPV2 protein expression in ESCC samples, we performed immunohistochemical staining on 62 tumor samples of Human ESCC using the TRPV2 antibody." (PMID 31690728, 2019). "S-TRPV2 is more typical for tumor cells including leukemic ones; it is localized in cytosol, and it inhibits full TRPV2 translocation to the cell membrane." (PMID 25866806, 2015). "Tumor xenografts derived from TRPV2-overexpressing GSC lines showed a significant reduction in diameter and mitotic index, associated with a GFAP-positive differentiated morphology." (PMID 24709905, 2014). "TRPV2 expression levels have been directly correlated with the tumor stage and grade of urothelial carcinoma (UC) of the human bladder." (PMID 24223658, 2013). "Furthermore, the activation of TRPV2 enhances the uptake of chemotherapeutic drugs, effectively overcoming tumor drug resistance." (PMID 40535121, 2025). "TUNEL staining of tumor tissues showed that the US, BG, and US combined with BG treatment groups all promoted apoptosis in TRPV2‐overexpressed tumors, with the US combined with BG treatment group showing a significantly enhanced proapoptotic effect compared to the BG group." (PMID 40013983, 2025). "Furthermore, TRPV2 that was mainly expressed in macrophages was activated during tumor progression to attract immunosuppressive components, such as macrophages, toward malignant cells for phagocytosis." (PMID 38948951, 2024). "Furthermore, the expression of TRPV2, TRPV4 and TRPV6 was found to increase according to the tumor stage with an association with poor prognosis, particularly in advanced stages." (PMID 39125864, 2024). "The analysis was stratified based on TRPV2 expression levels in the tumor samples." (PMID 39334351, 2024). "More importantly, TRPV2 KD attenuated tumor invasion and migration." (PMID 37138336, 2023). "The identification of functional TRPM4, TRPV2 expression in UVM may provide new drug targets for the treatment of this aggressive tumor disease." (PMID 36081847, 2022). "To further determine whether GPD1 promotes tumor cell apoptosis via TRPV2-mediated Ca2+ influx, we silenced the expression of TRPV2 with siRNA." (PMID 35836291, 2022). "Furthermore, these mesenchymal components often promote tumor progression themselves, further complicating the interpretation of TRPV2 mRNA expression in tumor biopsies." (PMID 34936030, 2021). "In line herewith, increased TRPV2 and TRPC1 mRNA expression levels were observed in both primary and metastatic EC biopsies and in primary EC cells with a high EMT status, indicating an association with an aggressive tumor phenotype." (PMID 34936030, 2021). "Numerous studies have shown that TRPV2 expression is related to tumor prognosis." (PMID 34579758, 2021). "Additionally, OS and PFS were calculated according to TRPV2 distribution, dividing patients according to TRPV2 expression in tumor, stroma, or both (tumor + stroma)." (PMID 32751388, 2020). "In vivo experiments with A549-TRPV2 xenografts further revealed showed that mice received combination treatment (TRPV2-PCNH mediated laser irradiation followed by PTX drug administration) exhibited strongest suppression in tumour growth as compared to single-approach treatments." (PMID 32807785, 2020). "Among TRPV channels, TRPV2 is a growth factor-regulated cation channel that was shown to be up-regulated in some cancer cell types, suggesting an oncogenic role, while down-regulated in other tumor cells, suggesting an opposite tumor suppression role." (PMID 33281564, 2020). "Consistent with the inactivated β-catenin function, RT-qPCR analyses of downstream targets of β-catenin signalling pathway also showed that, after laser irradiation, all target genes were significantly down-regulated in TRPV2 overexpressing cells and tumours pretreated with TRPV2–PCNH nanoparticles." (PMID 32807785, 2020).
tumor (continued). "Hence, we conclude that TRRV2–PCNH selectively impedes TRPV2 positive tumour progression following NIR laser irradiation in vivo." (PMID 32807785, 2020). "TRPV2 stable transfected Colon-26 cells was established to develop tumour syngeneic models." (PMID 32807785, 2020). "TRPV2 expression was found to increase according to tumor stage." (PMID 31083561, 2019). "Lysophospholipids and adrenomedullin stimulate insertion of the channel into the plasma membrane, and the subsequent TRPV2-mediated Ca2+ influx increases invasiveness of tumor cells via the direct regulation of key proteases such as MMP2, MMP9, and cathepsin B." (PMID 31288452, 2019). "In urothelial carcinoma, TRPV2 expression increased with increasing tumor stage and grade." (PMID 29066974, 2017). "The specific role of TRPV2 in carcinogenesis appears to differ according to tumor type." (PMID 29066974, 2017). "Other potential mechanisms linking TRPV2 to tumor development could be related to its ability to physically interact with proteins involved in cell proliferation and sensitivity to stretch stimuli." (PMID 24709905, 2014). "Oncogenic and Tumor suppressor effects of TRPV2 expression in different tumors." (PMID 24709905, 2014). "However, the expression level of TRPV2 channels in UC is significantly higher than in normal urothelial cells and is positively correlated with the clinical grade and stage of the tumor." (PMID 24223658, 2013). "However, this might be the result of TRPV2 activation for its antitumor effects during the tumor progression." (PMID 38948951, 2024). "Moreover, analysis of TRPV2 transcript levels according to the Clark staging system, defining anatomical invasion, revealed that higher the expression of TRPV2 was, the deeper the tumor had penetrated into the skin layers." (PMID 36744297, 2023). "Evidence suggests that TRPV1, TRPV2, and TRPV4 are overexpressed in several tumor types, contributing to processes such as tumor survival, proliferation, metastasis (migration and invasion), and angiogenesis." (PMID 40006844, 2025). "Laser-irradiated PCNH or TRPV2–PCNH NPs reduced the rate of HT-29 and HT-29-TRPV2 tumor growth in mice compared with those receiving PBS." (PMID 40548119, 2025). "The results showed that TRPV2 and TRPV3 were upregulated in ccRCC tumor tissues, whereas TRPV5 and TRPV6 were downregulated in tumor tissues." (PMID 35558077, 2022). "Our data showed that lysoPC converted from the GPD1 catalytic product G3P induced TRPV2 expression via PAFR to promote Ca2+ influx, which led to apoptosis of tumor cells." (PMID 35836291, 2022). "Further analysis of tumor immunologic characteristics and the correlation of ferroptosis with UVM revealed that TRPM4 and TRPV2 are considered as two novel prognostic biomarkers and promising targeted therapy in UVM." (PMID 36081847, 2022). "Some DEGs have been proved to play an important role in regulating tumor cell invasion ability such as WNT7A, VEGFA, EFEMP1, TRPV2, and FOXC2, whose expressions are consistent with the phenotype (see Results)." (PMID 35755807, 2022). "High expression of TRPM4 and TRPM7 was detected in primary tumor biopsies, while TRPV4, TRPC4, TRPC6 and especially TRPV6 expression was limited, while the expression of TRPC1 and TRPV2 are moderately expressed." (PMID 34936030, 2021). "In order to further demonstrate the practicability of the TRPV2-PCNH mediated phototherapy towards future medical use, the anti-tumour efficacy was next evaluated using immunocompetent mice." (PMID 32807785, 2020). "Fluorescent signals were stronger in HT-29–TRPV2 tumours than in HT-29 tumours throughout 48-h observations, suggesting sustained targeting of TRPV2–PCNH nanoparticles to TRPV2 overexpressing tumours." (PMID 32807785, 2020). "These channels such as TRPV1, TRPV2, as well as other numerous members of TRP channel family play a critical role in tumorigenesis, tumor vascularization, and the ability of tumor cells to proliferate and migrate." (PMID 31680972, 2019).
tumor (continued). "Amongst the large pore-cation non-selective ion channels, the TRP vanilloid subtype 2 channel (TRPV2), a member of the TRP superfamily, is highly expressed by a variety of tumor cells." (PMID 31680972, 2019). "The targeted gene TRPV2 was ruled out because it can simultaneously affect tumor metastasis and autophagy." (PMID 37138336, 2023). "In contrast, TRPC5, TRPV1, and TRPV2 channels have been found to impede macrophage differentiation, suppress HCC cell proliferation, and ultimately decrease tumor cell invasiveness through the Akt/IκB/NF-κB signaling pathway, STAT3 pathway, and Akt/Nrf2 signaling pathway, respectively." (PMID 37569884, 2023). "Transient receptor potential melastatin 7 (TRPM7) and vanilloid 2 (TRPV2) are nonselective cation channels that have become attractive target proteins for tumor studies due to their wide range of physiological and pathological functions 21-23." (PMID 35919815, 2022). "TRPA1, TRPV2, and TRPC3 were shown to be up-regulated in three different endothelial cell lines established from PCa patients as well as in endothelial cells lining tumor capillaries in vivo." (PMID 36430727, 2022). "While TRPV2 mRNA expression is mainly correlated to stage and invasion status of the cell, i.e., expression of MMPs, TRPC1 mRNA expression is increased in all cell lines that underwent EMT, regardless the tumor stage or MMP expression." (PMID 34936030, 2021). "In contrast, EM012 cells, which are derived from a stage IV tumor and are expressing high levels of TRPV2 mRNA, do not express both mesenchymal marker proteins." (PMID 34936030, 2021). "Especially TRPV2 and TRPC1 mRNA expression could serve as potential biomarkers for tumor invasiveness." (PMID 34936030, 2021). "Inoculation of 500 cells from tumours without irradiation (PBS and TRPV2–PCNH groups) resulted in aggressive tumour development with a tumour formation rate of 100%." (PMID 32807785, 2020). "HT-29–TRPV2 tumours were more strongly suppressed under these conditions in the TRRV2–PCNH + Laser group than in the other treatment groups, perhaps indicating selective targeting of TRPV2-overexpressing cells by TRRV2–PCNH." (PMID 32807785, 2020). "Overall, our results indicated that high levels of NALCN, TRPC1, TRPV2, and CACNA1H could be suggestive of an advanced stage tumor." (PMID 31083561, 2019). "Finally, we discuss the role of endothelial TRP channels in aberrant tumor vascularization by focusing on TRPC1, TRPC3, TRPV2, TRPV4, TRPM8, and TRPA1." (PMID 32038296, 2019). "Cannabidiol (CBD) is a non-psychoactive cannabinoid with anti-tumor activities, acting as a TRPV2 agonist." (PMID 31801263, 2019). "Transient receptor potential vanilloid 2 (TRPV2), a nonselective cation channel, has become an attractive target gene for tumor studies due to its wide range of physiological and pathological functions." (PMID 24223658, 2013). "Simply opening the TRPV2 channel itself is not sufficient to induce the desired therapeutic effects, as it alone does not lead to a significant increase in intracellular calcium ion concentration in tumor cells." (PMID 40013983, 2025). "Additionally, ADM was demonstrated to influence the translocation of transient receptor potential vanilloid 2 (TRPV2) to the plasma membrane through PI3K pathway, leading to increased resting calcium levels in tumor cells, thereby contributing to its effect on tumor cell migration." (PMID 40565016, 2025). "Interestingly, we observed higher levels of TRPV2 expression in the tumor area compared to adjacent non-tumor tissue." (PMID 39334351, 2024). "Therefore, the biological role of TRPV2 in non-malignant cell types within the tumor microenvironment should be examined alongside ectopic TRPV2 expression within malignant cells." (PMID 34936030, 2021).